MTOR (mechanistic target of rapamycin kinase)
Diseases named in the same sentence as MTOR in open-access papers (continued):
Sharing a sentence is not in itself a finding about the gene and the disease.
atherosclerosis (continued). "Mainly, the anti-proliferative effect of mTOR inhibitors may have benefits on atherosclerosis and reduces the risk of CV disease." (PMID 30473931, 2018). "Our results suggest that atherosclerosis-associated endothelial cell apoptosis might result from abundant miR-210 that inhibits P13K/Akt/mTOR signaling activation by directly targeting PDK1." (PMID 28536634, 2017). "Furthermore, mTOR inhibition may mitigate cardiovascular risk by modulating cholesterol metabolism and attenuating atherosclerosis progression." (PMID 38928483, 2024). "Decreased brain perfusion during normative aging has been established (Melamed, Lavy, Bentin, Cooper, & Rinot, 1980), and we recently showed that mTOR mediates cerebrovascular dysfunction in two different mouse models of AD and in a model of cognitive impairment associated with atherosclerosis." (PMID 31693798, 2020). "Independently, mTOR activation controls stem cell development, promotes pancreatic β-cell proliferation, prevents apoptosis, limits insulin resistance, blocks vascular thrombosis in patients with metabolic syndrome, and prevents pathways associated with atherosclerosis." (PMID 26064426, 2015). "Further research is needed to fully understand the net cardiovascular effects of mTOR inhibitors and their role in atherosclerosis development." (PMID 40003654, 2025). "In atherosclerosis, mTOR activation drives several processes contributing to plaque formation and instability." (PMID 40734978, 2025). "For example, the binding of CXCR4 to CXCL12 promotes macrophage autophagy through the PI3K/AKT/mTOR pathway, which alleviates atherosclerosis and improves myocardial structure." (PMID 40535169, 2025). "MiR-125b-1-3p ameliorates atherosclerosis in mice by enhancing autophagy in the VMSCs via the RRAGD/mTOR/ULK1 axis." (PMID 40823532, 2025). "Dysregulation of mTOR can lead to the excessive apoptosis of endothelial cells, VSMCs, and cardiomyocytes, contributing to the progression of diseases such as atherosclerosis, myocardial infarction, and aortic dissection." (PMID 40734978, 2025). "Our study elucidates a previously unrecognized synergy between NGR1 and SSB2 in combating atherosclerosis through PI3K/Akt/mTOR pathway inhibition and autophagy restoration." (PMID 40577270, 2025). "This further corroborates the significance of the PI3K/AKT/mTOR pathway in the pathological progression of atherosclerosis." (PMID 40577270, 2025). "Atherosclerosis development is predominantly observed in regions with low shear stress, associated with decreased AMPK expression and increased mammalian target of rapamycin (mTOR) expression, leading to impaired autophagy." (PMID 40427496, 2025). "KEGG analysis revealed enrichment in pathways such as “lipid and atherosclerosis”, “mTOR signaling pathway”, “ferroptosis”, “TNF signaling pathway”, and “Th17 cell differentiation”." (PMID 41515900, 2025). "Overall, targeted modulation of mTOR signaling offers a promising avenue for atherosclerosis therapy, but further clinical validation is required." (PMID 40871049, 2025). "This pioneering study provides compelling evidence that the combination of NGR1 and SSB2 (NS) effectively mitigates inflammation and inhibits the activation of the PI3K/Akt/mTOR signaling pathway in atherosclerosis." (PMID 40577270, 2025). "This persistent activation of mTOR accelerates the development of atherosclerosis, increases plaque vulnerability, and contributes to plaque rupture, a key event in the pathogenesis of acute coronary events." (PMID 40734978, 2025). "The AMPK/mTOR pathway plays a crucial role in the development and progression of atherosclerosis and fatty liver by modulating oxidative stress and inflammatory processes." (PMID 41225688, 2025). "Astragaloside IV, another TCM bioactive, attenuates atherosclerosis via the PI3K/Akt/mTOR pathway activation, reducing oxidative stress and improving lipid metabolism in apoE−/− models, further underscoring the multi-target potential of TCM." (PMID 40872505, 2025).
atherosclerosis (continued). "The mammalian target of rapamycin (mTOR) signaling pathway is a central regulator of cell metabolism, growth, and survival, and plays a critical role in atherosclerosis." (PMID 40871049, 2025). "Blockade of CXCR4 can inhibit the activation of CXCR4 after binding with CXCL12 and regulate autophagy through the PI3K/AKT/mTOR pathway to improve and reduce atherosclerosis and improve cardiac structure." (PMID 40535169, 2025). "This has great therapeutic potential, firstly proven in atherosclerosis, especially because macrophages’ ability to accumulate cholesterol depends mostly on the mTOR axis driven by oxidized low-density lipoprotein (oxLDL)." (PMID 40806725, 2025). "The RAGE/ILK/mTOR/p70S6K signalling pathway is another key player in the advancement of atherosclerosis, with ILK acting as a versatile intracellular serine/threonine kinase that contributes to the pathogenesis of the disease." (PMID 40959494, 2025). "KEGG analysis showed that NDEGs were mainly enriched in MAPK signaling pathway, lipid and atherosclerosis, mTOR signaling pathway, JAK-STAT signaling pathway, prolactin signaling pathway, glycerophospholipid metabolism and other pathways." (PMID 40433461, 2025). "Regulates autophagy through the PI3K/AKT/mTOR pathway, alleviating atherosclerosis, and improving myocardial structure." (PMID 40535169, 2025). "This mechanistic insight extends prior work demonstrating mTOR as a negative regulator of autophagy in atherosclerosis, and highlights NS as a potential dual inhibitor of PI3K/Akt/mTOR signaling." (PMID 40577270, 2025). "In atherosclerosis, hyperactivation of the mTOR pathway exacerbates oxidative stress and foam cell apoptosis, destabilizing plaques and promoting vascular inflammation." (PMID 40734978, 2025). "KEGG pathway analysis further indicated significant enrichment in the TGF-β signaling pathway, Hippo signaling, and mTOR pathways, as well as pathways related to fluid shear stress, atherosclerosis, and adipocytokine signaling." (PMID 41261618, 2025). "This notion is supported by the fact that inflammatory signaling involving mTOR plays a critical role in atherosclerosis and inhibiting mTOR is therapeutically beneficial." (PMID 38817407, 2024). "We observed that the differentially expressed genes were mainly enriched in the ErbB signaling pathway, TGF-β signaling pathway, mTOR signaling pathway, apoptosis, proteoglycans in cancer, fluid shear stress, and atherosclerosis." (PMID 38175694, 2024). "A recent study identified the individual roles of Leu in plasma, revealing that higher blood Leu levels activate mTOR signaling pathway in human and mouse monocytes/macrophages, which in turn promotes atherosclerosis in mice." (PMID 39766264, 2024). "DCLK1, EGFR, and MTOR (all connected to the ATP binding pathway) have been identified as potential therapeutic targets for atherosclerosis." (PMID 39796045, 2024). "The knockdown of CXCR4 alleviates the degree of CHD by promoting macrophage autophagy through the PI3K/AKT/mTOR pathway to reduce atherosclerosis." (PMID 39590363, 2024). "A previous study discovered that ginkgo biloba leaf extract alleviates atherosclerosis in streptozotocin-induced diabetic ApoE−/− mice by restraining ER stress via autophagy restoration using the mTOR signaling pathway." (PMID 39119608, 2024). "Indeed, while mTOR signaling plays a crucial role in controlling the immune system, the hyperactivation of mTOR1 not only hinders cells transitioning into a memory state but has also been linked to general inflammation, cardiovascular disease, and atherosclerosis." (PMID 38338233, 2024). "Metabolism of arginine and proline; digestion and absorption of fat, lipids, and atherosclerosis; biosynthesis of neomycin, kanamycin, and gentamicin; and the mTOR signaling pathway were enriched after the addition of BL probiotics." (PMID 39065178, 2024).
atherosclerosis (continued). "For example, the ncRNA Chaer regulates H3K27me3 and interacts with the polycomb repressor complex (PRC) 2, promotes cell proliferation, and induces apoptosis in atherosclerosis involving mammalian target of rapamycin (mTOR) signaling." (PMID 39796562, 2024). "Danlou Tablets promote macrophage autophagy by inhibiting the PI3K/Akt/mTOR signaling pathway to reduce foam cell formation and improve atherosclerosis." (PMID 38952541, 2024). "The role of mTOR in atherosclerosis is supported by the increased mRNA expression in RAPA treated with LR-12 and scrambled peptide compared to their counterpart." (PMID 38817407, 2024). "Conversely, the activation of EGFR will lead to the activation of the PI3K/AKT/mTOR signaling pathway, which plays an important role in pathophysiological processes such as hyperlipidemia and atherosclerosis." (PMID 38920980, 2024). "Ji and coworkers found that resveratrol downregulates the PI3K/AKT/mTOR signaling pathway in vitro in umbilical vein endothelial cells obtained from an atherosclerosis mice model." (PMID 38138958, 2023). "Inflammation-induced Akt/mTOR/NF-κB activation has been observed in many inflammatory diseases, such as Crohn’s disease, celiac disease, atherosclerosis, and cardiovascular disease." (PMID 38102220, 2023). "According to the gene functional enrichment analysis (GO and KEGG), there were noteworthy differences in immune-related pathways between the two groups, including microRNAs in cancer, fluid shear stress and atherosclerosis, and the mTOR signaling pathway." (PMID 37511932, 2023). "In this context, mTOR inhibition is profitable in the treatment of many cardiovascular diseases, including atherosclerosis." (PMID 37108307, 2023). "Attributable to the pleiotropic effects of mTOR on vascular cell activation and foam cell lipid metabolism, mTOR inhibition has been proposed as a promising therapeutic approach to atherosclerosis." (PMID 37894840, 2023). "The effects exerted by mTOR inhibition can contribute to its therapeutic effects in ameliorating atherosclerosis in animal models of atherosclerosis." (PMID 37108307, 2023). "A large number of documents have shown that PI3K/Akt/mTOR pathway affects the process of atherosclerosis, heart failure, myocardial I/R and other diseases." (PMID 37063954, 2023). "Another recent study showed an interaction between miR-214-3p and MAPK/mTOR signaling pathways in the atherosclerosis mice model." (PMID 38132140, 2023). "KEGG pathway analysis revealed that the genes were involved in some classical lipid-related pathways, such as the “MAPK signaling”, “lipid and atherosclerosis”, “mTOR signaling, and “FoxO signaling” pathways." (PMID 37511041, 2023). "The KEGG pathway analysis results also showed that the differentially expressed genes were significantly enriched in immune-related pathways, including microRNAs in cancer, fluid shear stress and atherosclerosis, and the mTOR signaling pathway." (PMID 37511932, 2023). "The precise function of mTOR in these pathologies will be emphasized using myocardial infarction (MI) and atherosclerosis as two notable instances of CVD defined by pathophysiological mechanisms comprising acute and chronic inflammation, respectively." (PMID 35845058, 2022). "Nevertheless, mTOR inhibitors ameliorated dyslipidemia‐induced senescence of ECs and VSMCs, which was protective in atherosclerosis." (PMID 35569818, 2022). "Pivotal implications of mTOR-signaling are further identified for cardiovascular diseases like acute myocardial infarction, myocardial hypertrophy, atherosclerosis, and cardiomyopathies." (PMID 35845058, 2022). "This review presents current information and concepts of mTOR activity in myocardial infarction and atherosclerosis, two important instances of cardiovascular illness involving acute and chronic inflammation." (PMID 35845058, 2022).
atherosclerosis (continued). "In atherosclerosis, mTOR-dependent B2 cells are considered pro-atherosclerotic B1 cells and B regs also depend on mTOR-activity." (PMID 35845058, 2022). "Based on the available data, the use of drugs that modify the mTOR signaling pathway in the treatment of atherosclerosis is controversial." (PMID 35163076, 2022). "Evidence for beneficial effects of mTOR-modulation in atherosclerosis comprises observation of reduced smooth muscle cell proliferation and macrophage influx as well as decreasing lipid metabolism and neo angiogenesis after mTOR inhibition." (PMID 35845058, 2022). "Yet, several experimental models in atherosclerosis and myocardial infarction provide evidence that mTOR inhibition in DCs lead to a beneficial outcome." (PMID 35845058, 2022). "Rapamycin (Rap) with 5 μM (4.57 μg/mL) inhibits the formation of foam cells (which is an early sign of atherosclerosis) by blocking activation of the mammalian target of rapamycin (mTOR)." (PMID 35631669, 2022). "KEGG pathway results showed that the top 20 pathways were mainly enriched in the PI3K-Akt signaling pathway, adrenergic signaling in cardiomyocytes, fluid shear stress and atherosclerosis, the mTOR signaling pathway, and the Rap1 signaling pathway." (PMID 36059969, 2022). "Further, mTOR inhibition results in relevant developmental changes in specific subpopulations of immune cells relevant for the course of the disease in either atherosclerosis or myocardial infarction." (PMID 35845058, 2022). "Apocynum leaf extract can marked increase the p-AMPK but decrease the mTOR protein expression to reduce blood lipid levels in rats with atherosclerosis and delay atherosclerotic progression." (PMID 35291946, 2022). "This pathway is closely associated with atherosclerosis, and the pro-inflammatory response of monocytes in CAD requires activation of mTOR." (PMID 35529472, 2022). "In summary, our results suggested that DLTs can promote autophagy in macrophages by inhibiting the PI3K/Akt/mTOR signaling pathway, thereby reducing foam cell formation and improving atherosclerosis." (PMID 34566648, 2021). "This evidence suggests that Danlou tablets can activate PI3K/Akt/mTOR-mediated autophagy to improve atherosclerosis." (PMID 34867337, 2021). "Inhibition of autophagic factors, such as ATG5, increases atherosclerosis in hypercholesterolemic mice, and excess dietary protein in these models has recently been found to exacerbate atherosclerosis by a mTOR dependent inhibition of autophagy." (PMID 33984028, 2021). "A recent study found that activation of P2RY12 receptor activated mTOR through PI3K/AKT to block autophagy in advanced atherosclerosis and reduce cholesterol outflow." (PMID 33767629, 2021). "This miRNA also diminishes endothelium damage through restoration of autophagic flux by suppressing the PI3K/Akt/mTOR signaling in in vitro model of atherosclerosis." (PMID 34299680, 2021). "Curiously, they also report that deletion of macrophage mTOR, ablating both mTOR-dependent pathways, leads to residual alterations in atherosclerosis, reflecting the opposing effects of these two signaling pathways." (PMID 33855029, 2021). "The dysfunction of lysosomes in lipid degradation, macrophage polarization, generation of lipid signaling intermediates or mTOR activation can have profound effects on the development of atherosclerosis." (PMID 34447787, 2021). "The amino acid sensing by mTOR and the pivotal role of mTOR in atherosclerosis development are now well illustrated." (PMID 33990205, 2021). "In the initial stage of atherosclerosis the activation of mTOR signaling contributes to the formation of foam cells via enhancing the process from monocyte to macrophage." (PMID 32849539, 2020). "As the specific inhibitor of mTOR, rapamycin has been applied in clinical treatment of atherosclerosis to suppress VSMCs proliferation and migration." (PMID 33071810, 2020).
atherosclerosis (continued). "In other work, Chaer in patients with atherosclerosis was highly expressed when compared with healthy individual, suggesting that Chaer promoted atherosclerosis by mediating PRC2 activity via the mTOR signalling pathway." (PMID 33052009, 2020). "Endothelial pro-inflammatory activation plays a pivotal role in atherosclerosis, and many pro-inflammatory and atherogenic signals converge upon mechanistic target of rapamycin (mTOR)." (PMID 31728028, 2019). "In this study, we have revealed the possibility of nicotine accelerating atherosclerosis via nAChRα1/STAT3/Akt/mTOR signaling pathway." (PMID 31612866, 2019). "Taken together, STAT3 and nAChRα1 blockade attenuates nicotine-induced atherosclerosis by reducing the migration and proliferation of vascular smooth muscle cells and inflammation in macrophages via the Akt/mTOR pathway." (PMID 31612866, 2019). "The network pharmacology utilized in the present study predicted that ginkgo biloba leaf attenuates atherosclerosis through mTOR and NF-κB-mediated inflammation signaling pathways." (PMID 31080547, 2019). "PI3K/AKT/mTOR pathway plays a role in endothelial function and in the development of atherosclerosis." (PMID 30305865, 2018). "The mammalian target of rapamycin (mTOR) that controls autophagy and lipid metabolism is pivotal for atherosclerosis initiation and progression." (PMID 29629115, 2018). "In this study, we engineered a cerium oxide nanowire (CeO2 NW)-based RNA interference (RNAi) oligonucleotide delivery nanoplatform for the effective silencing of mTOR and treatment of atherosclerosis." (PMID 29629115, 2018). "mTOR/p70S6K signalling has been reported to function as a critical regulator in the development of atherosclerosis, and the inhibition of mTOR has reportedly suppressed the development of atherosclerosis." (PMID 29571225, 2018). "A H2O2-responsive and plaque-penetrating S2P–CeO2–ASOs nanoplatform was developed for the effective silencing of mTOR and treatment of atherosclerosis." (PMID 29629115, 2018). "In the present study, we demonstrated that FA ameliorated atherosclerosis progression via suppression of the mTOR/p70S6K signalling pathway." (PMID 29571225, 2018). "Here, we found that M1 macrophages can enhance autophagy by inhibiting mTOR signaling, a key regulator of atherosclerosis." (PMID 30627532, 2018). "Our findings also showed that PDK1 is an essential miR-210 target in regulating endothelial apoptosis of atherosclerosis by inhibiting P13K/Akt/mTOR signaling activation." (PMID 28536634, 2017). "We were interested in determining the involvement of PDK1 and P13K/Akt/mTOR signaling in the miR-210 regulatory apoptotic effect in atherosclerosis." (PMID 28536634, 2017). "Our study identified the pro-atherosclerotic role of miR-210 by promoting endothelial apoptosis partially through targeting PDK1 to suppress the P13K/Akt/mTOR signaling pathway, providing new insight into the treatment of atherosclerosis." (PMID 28536634, 2017). "Together, our results demonstrate that disturbed flow influences endothelial function and induces atherosclerosis in an mTOR/DNMT1-dependent manner." (PMID 29118325, 2017). "Similar results were obtained as vitro results under transmission electron microscope: vacuoles with cytoplasmic inclusions and myeline figure displayed in the atherosclerosis segment after rabbits were treated with triciribine, rapamycin and mTOR-siRNA." (PMID 24599185, 2014). "In the process of atherosclerosis, a number of factors mediate mTOR activation and subsequently down-regulate the macrophage autophagy." (PMID 24599185, 2014). "In conclusion, selectively inhibition of Akt/mTOR pathway can inhibit the atherosclerosis progression and enhance the stability of atherosclerotic plaques by activation of macrophage autophagy." (PMID 24599185, 2014).